TLR4 (toll like receptor 4)
Diseases named in the same sentence as TLR4 in open-access papers (continued):
Sharing a sentence is not in itself a finding about the gene and the disease.
Sepsis (continued). "Additionally, it opens the discussion for new treatment modalities, such as anti-TLR4 antibodies and TLR4 antagonist; some compounds from the latter class are already under clinical trials for treatment of sepsis in human patients." (PMID 23016675, 2012). "The aim of this study was to investigate the role of TLR2, TLR4 and MyD88 in sepsis-induced AKI." (PMID 22655058, 2012). "Indeed, our data support this explanation by demonstrating that SRA interacts with TLR4 in CLP sepsis." (PMID 23071440, 2012). "Surface TLR4 expression allows discriminating sepsis and SIRS." (PMID 23098236, 2012). "It is beyond the scope of this study to speculate as to how NOD1 and TLR4 mediated inflammation might proceed throughout the blood vessel over longer periods of sepsis." (PMID 22870324, 2012). "Since TLR 4 acts as the receptor that signals LPS bioactivity in sepsis, the TLR4/uric acid/Weibel-Palade axis might work as the proposed 'vascular danger signals' that agonizes EPCs in the bone marrow to migrate into the circulation." (PMID 21396100, 2011). "Until now, no other SNPs or haplotypes of TLR4 were found to be associated with the susceptibility of sepsis or infectious diseases among Asian populations." (PMID 21219635, 2011). "To test this hypothesis, we conducted a case control study using a tag SNP approach to investigate the association of variants in TLR2, TLR4, TLR9, MyD88, and TOLLIP with susceptibility to sepsis in the Chinese Han population." (PMID 21219635, 2011). "Over activation of TLR4 can give rise to endotoxic shock often resulting in sepsis and death." (PMID 21809339, 2011). "Since the TLR-4 pathway mediates the hepatic response to invading bacteria, we hypothesized that the combined effects of sepsis and feeding WD on TRL-4 signaling would exacerbate hepatic inflammation in septic mice." (PMID 20958969, 2010). "The purpose of this paper is to focus on various drugs interfering with TLR4 expression or TLR4-related intracellular pathway and their potential role as adjunctive therapy in severe sepsis and septic shock, or as modulator of the TLR4-induced inflammatory response." (PMID 20396414, 2010). "We also found that −2242T/C and 11367G/C were two functional SNPs in TLR4 gene and may be related to sepsis morbidity." (PMID 21274447, 2010). "Since lipopolysaccharide (LPS) or endotoxin is a specific ligand for TLR4, and because TLR4 expression is increased on human monocytes in healthy volunteers undergoing LPS challenge, and in patients with sepsis, particular attention has been made to this receptor and signalling pathway." (PMID 20396414, 2010). "Thus, our finding that TLR4−/− mice respond differently than WT mice to S. aureus sepsis is in line with the literature." (PMID 20657826, 2010). "TLR4 antagonists are trying to be applied to treatment of sepsis." (PMID 20672047, 2010). "We hypothesize that monocyte hyporesponsiveness in human sepsis is associated with a downregulation of the pattern recognition receptors Toll-like receptor (TLR)-2 and TLR4." (PMID 19371402, 2009). "This profile is extremely appealing as recent data using TLR4 antagonists suggest that a modulation of pro-inflammatory cytokine release could be beneficial in sepsis." (PMID 19740426, 2009). "In the present study we aimed to characterize the expression and function of TLRs in sepsis caused by B. pseudomallei and found that, although both TLR2 and TLR4 contribute to cellular responsiveness to B. pseudomallei in vitro, only TLR2 impacts on the immune response of the intact host in vivo." (PMID 17676990, 2007). "Importantly, Z-CDs exerted potent inhibitory effects on NF-κB nuclear translocation through dose-dependent suppression of IκBα degradation and p65 phosphorylation, suggesting selective disruption of the TLR4/NF-κB signaling axis—a central mediator of sepsis-induced organ dysregulation." (PMID 40217355, 2025).
Sepsis (continued). "Indeed, the mutual facilitatory interaction between PI3K and MAPK entities are key components of the hyperinflammatory phase of sepsis triggered by TLR4, the sensing receptor for microbial structures such as bacterial lipopolysaccharides and associated molecular patterns." (PMID 40573276, 2025). "In the future, multi-organ protective intervention strategies need to be developed by targeting the TLR4 pathway, clearing circulating LPS, and regulating the microbiota-immune axis to contain the uncontrolled inflammation and organ failure driven by microbial products in sepsis." (PMID 41244772, 2025). "Further animal experiments have confirmed that HD can significantly improve pulmonary edema and pathological damage, suggesting that targeting the TLR4 pathway, clearing circulating LPS, and regulating the microbiota-immune axis may become new strategies for the treatment of sepsis." (PMID 41244772, 2025). "Since P12 was found to inhibit TLR4 signaling and downstream inflammatory responses in macrophages, we hypothesized that it may regulate the inflammatory macrophages to suppress systemic inflammation in sepsis to exert cerebroprotective effects in SAE mice." (PMID 40236814, 2025). "Thus, the natural multifunctional AMPs could serve as a model for de novo designing functionality-directed synthetic AMPs that can simutaneously regulate TLR4/2 signaling and eradicate bacteria to combat sepsis." (PMID 40963927, 2025). "Notably, TLR signaling pathway analysis revealed that TLR2 and/or TLR4 deficiency substantially attenuated IGFBP6 expression in PLF, pulmonary tissue, macrophages, and epithelial cells during sepsis, establishing TLR2/4-mediated regulation of IGFBP6 production." (PMID 40892465, 2025). "Thus, activated brain pericytes may play a role in the initial inflammatory response during sepsis through the release of cytokines and chemokines mediated by LPS-induced TLR4/Myd88 signaling, with Fli-1 acting as a crucial regulator in this process." (PMID 39862276, 2025). "Additionally, specific risks exist for different targets; for instance, systemic TLR4 agonists may induce sepsis-like reactions, while TLR7/8/9 agonists require attention to their potential risk of inducing autoimmune-like symptoms." (PMID 41568029, 2025). "Thus, multifunctional therapeutic agents that simultaneously inhibit both TLR2 and TLR4 activation while killing bacteria may serve as a promising strategy to combat sepsis." (PMID 40963927, 2025). "TLR4 expression is detectable across a spectrum of immune cells, endothelial cells, and alveolar epithelial cells, where it orchestrates a series of reactions that govern cellular metabolic alterations and exerts a pivotal influence on the progression of sepsis-induced lung injury." (PMID 39712019, 2024). "All these data indicate that TLR4 may significantly contribute to the pathogenesis of SARS-CoV-2 indicating TLR4 as a promising therapeutic target in COVID-19, which is supported also by the fact that TLR4 antagonists have been previously used in sepsis and in other antiviral contexts." (PMID 38791489, 2024). "Although CFU enumeration seems to suggest bacterial clearance following PMB treatment, the initial high blood bacterial density achieved early in the infection may have been sufficient to trigger sepsis and lead to TLR4-mediated hyperinflammation and lethality." (PMID 39240097, 2024). "Moreover, higher expression of Rab5a and surface TLR4 were found in peripheral blood monocytes of patients with sepsis than in the normal control group, and both were correlated with the SOFA score of sepsis patients, with a higher expression of Rab5a found in septic non-survivors." (PMID 38549133, 2024). "For example, the genetic polymorphism rs11536889 in TLR4 is linked to an increased risk of Gram-negative bacterial infections, as well as coagulation dysfunction, renal and hepatic dysfunction or organ failure in sepsis patients." (PMID 38835773, 2024).
Sepsis (continued). "Additionally, TLR4-dependent internalization of CX3CR1 may exacerbate sepsis-induced immunoparalysis." (PMID 38245687, 2024). "Given the importance of these factors to the immune response, therapeutic methods focusing on exploring the possible mechanisms involved in TLR4 trafficking, the regulation of Rab5a expression, and the amount of TLR4 on macrophage surfaces, may be effective strategies for treating sepsis." (PMID 38549133, 2024). "During sepsis, LPS binding to TLR-4 may activate the JNK, ERK, or p38 MAPK pathways or the mitochondria-mediated intrinsic apoptosis pathway, which in turn activates caspase-3, an apoptosis activator effector, and downregulates Bcl-2, an inhibitor of apoptosis." (PMID 37900081, 2023). "The LPS/TLR4 signaling pathway may induce massive inflammation and lead to sepsis." (PMID 37650558, 2023). "Therefore, we speculated that the protective effects of TLR4 silencing on sepsis-induced AKI mice might be achieved by regulating cell pyroptosis." (PMID 37605037, 2023). "Therefore, it suggested that inhibition of TLR4 could improve clinical outcomes in patients with sepsis." (PMID 36629024, 2023). "Moreover, regarding the TLR4/ NF‐κB signalling pathway, during sepsis, LPS enters the renal tubule via the site of infection or distal injury via renal tubular filtration and other mechanisms, resulting in widespread expression of TLR4 in the kidney, which recognizes LPS and activates NF‐κB." (PMID 37667551, 2023). "Thus, it is a promising strategy to modulate TLR4 to treat sepsis." (PMID 38455195, 2023). "Nevertheless, whether PICK1 can regulate the inflammatory response mediated by the TLR4/NF-κB pathway in sepsis and the underlying mechanisms involved have not yet been reported." (PMID 37488153, 2023). "Therefore, our results imply that TLR4/MyD88/NF-κB signaling may take part in the effect of EA at ST36 against sepsis." (PMID 35722155, 2022). "Therefore, TLR4 is an attractive therapeutic target for immunological disorders such as sepsis." (PMID 36230982, 2022). "Therefore, the activation of Notch signal in sepsis may play an important role in the enhancement of the inflammatory response induced by TLR4 in the heart." (PMID 35891967, 2022). "Therefore, targeting miR-578/TLR4 axis could serve as potential therapeutic approach to ameliorate kidney damages in sepsis-induced AKI." (PMID 35510365, 2022). "In addition, the regulation of sepsis may be correlated with TLR4/MyD88/NF-κB signaling and alterations to the intestinal flora." (PMID 35722155, 2022). "Therefore, TLR4 is a promising target in the treatment and intervention of sepsis." (PMID 35280898, 2022). "Cardiac inflammation caused by severe systemic congestion is also included in the indirect mechanism, but it should be the third mechanism itself, because it may involve sepsis, toll-like receptor 4 (TLR4) activation and/or cytokine storm (also called “immune mediated cytokine release syndrome”)." (PMID 35387441, 2022). "The mechanism of TLR4 in intestinal epithelial cell damage in sepsis remains unclear." (PMID 36088483, 2022). "In addition to impairment of endothelial function, vascular smooth muscle cells (VSMCs) also contribute to vascular dysfunction through the activation of toll-like receptor 4 (TLR4) which is also involved in the sepsis-induced hyporesponsiveness to vasoconstrictors." (PMID 35795581, 2022). "However, blocking the whole TLR4 pathway may result in the failure of follow-up anti-infective treatment given that burn sepsis is an aggravation of systemic inflammatory response." (PMID 35280898, 2022). "In addition, toll-like receptor 4 (TLR4) and p65 exert significant functions in sepsis-induced AKI." (PMID 35038964, 2022).
Sepsis (continued). "However, antibody drugs targeting cytokines (e.g., tumor necrosis factor [TNF] and interleukin 6 [IL6]), inflammatory pathways (e.g., toll like receptor 4 [TLR4]), or endotoxin, as well as empiric antibiotic therapies have little or disappointing benefit for patients with sepsis." (PMID 33776776, 2021). "We report that BM-derived megakaryocytes and blood platelets both express TLR4 on their surface, as assessed via flow cytometry, prompting us to assess the effect of loss of Caspase-8 and MLKL on platelet production and clearance in an in vivo LPS-induced sepsis model." (PMID 33510145, 2021). "After the activation of TLR, HMGB1 could acetylate and trigger its translocation from the nucleus to the circulation and interact with a variety of target cell receptors (RAGE, TLR2, TLR4, etc.), stimulating the release of pro-inflammatory cyto-/chemokines and leading to inflammations and sepsis." (PMID 34938184, 2021). "It is therefore possible that in conditions as encountered during sepsis where several molecular species of lipid A are present, the joint existence of the two TLR4:MD2 signaling pathways may allow incomplete forms of lipid A to contribute to inflammation through synergistic or antagonistic effects." (PMID 34409274, 2021). "Thus, it is reasonable to hypothesize that TLR4 or RAGE inhibition might prevent cell death in sepsis." (PMID 34733114, 2021). "Thus, TLR4 inhibitors or CD38 activators may serve as potential drugs to attenuate E. coli-induced liver injury in septicemia." (PMID 33860064, 2021). "Moreover, toll-like receptor 4 (TLR4) plays a crucial role in the pathogenesis of inflammatory diseases, and the activation of TLR4 during sepsis may be related to the stimulation of lipopolysaccharide (LPS) endotoxin." (PMID 34457021, 2021). "TAK 242 (resatorvid) is a specific TLR4 inhibitor that has potent anti-inflammatory activity in a variety of inflammatory diseases, including endotoxemia-induced skeletal muscle wasting, sepsis, acute kidney injury, neuroinflammation, acute cerebral ischemia, cancer, and rheumatoid arthritis." (PMID 34884814, 2021). "The present study aims to investigate the effects of Fer-1 on LPS-induced cardiac dysfunction and whether Fer-1 exerts its function in sepsis-induced cardiac dysfunction by inhibiting ferroptosis and inflammation, and modulating the TLR4/NF-κB signaling pathway." (PMID 34787054, 2021). "Therefore, Fer-1 may regulate sepsis-induced cardiac dysfunction via the TLR4/NF-κB signaling pathway." (PMID 34787054, 2021). "However, the disappointing results of TLR4 inhibitors as anti-sepsis drugs in clinical trials indicate that a more important, TLR4-independent mechanism for LPS-induced injury may exist." (PMID 32332915, 2020). "Therefore, in this study, we investigated the roles of sesamin in regulating the development of sepsis via the HMGB1/TLR4/IL-33 signalling pathway by examining its impacts on the production of pro-inflammatory cytokines and the expression of IL-33, HMGB1, TLR4, ZO-1, and occludin." (PMID 32893702, 2020). "Moreover, multiple studies on animal models of sepsis found that suppression HMGB1/TLR4/NF-κB signaling pathway could attenuate inflammation response and ultimately reduce the damage of vital organs as well." (PMID 33552058, 2020). "Hence, we hypothesized that miR-17-5p and TLR4 might be involved in NEAT1-mediated inflammation in sepsis." (PMID 32099901, 2020). "However, different therapeutic strategies aiming at inhibiting LPS binding to TLR4 failed to improve the outcome of severe sepsis patients (no reduction in 28-day and 1-year all-cause mortality)." (PMID 31197574, 2019). "Therefore, it can be suggested that isorhamnetin binds to MD-2, resulting in the inhibition of the TLR4/MD-2 dimerization, which may eventually downregulate the activation of TLR4 pathway-induced inflammation and sepsis." (PMID 31689976, 2019).
Sepsis (continued). "Furthermore, based upon binding affinity and a molecular docking examination, we show for the first time, to our knowledge, that isorhamnetin can bind TLR4/MD-2 directly, thus preventing the activation of the TLR4 cascade, which is responsible for sepsis progression." (PMID 31689976, 2019). "Additionally, it has been demonstrated that baseline monocyte TLR4 expression is increased in septic compared to healthy neonates and that isolated neutrophils and monocytes from adults with sepsis have higher mean fluorescence for TLR4 expression than cells from controls." (PMID 31612119, 2019). "Based on these previous findings, the hypothesis that TLR4 signaling is required to trigger the release of IL-1β under conditions of systemic inflammation appears quite plausible, although TLR4 on DCs are known to regulate inflammatory neutrophils or spleen DCs during sepsis." (PMID 31323786, 2019). "It seemed that SND therapy helped the adrenal TLR4 to stay at relatively appropriate levels and helped the adrenal stress systems to remain in competent coordinated response, which might be crucial for survival in sepsis." (PMID 30018657, 2018). "Preclinical and clinical studies have evaluated Eritoran tetrasodium, a compound that interferes with TLR4/MD-2/LPS, inhibiting the LPS-induced release of TNF-α, IL-β and IL-6, thus limiting excessive inflammation associated with TLR4 activation, as a potential therapeutic for sepsis." (PMID 29882798, 2018). "For example, lipopolysaccharide (LPS) derived from Gram-negative bacteria, may cause sepsis by engaging Toll-like receptor 4 (TLR4) on phagocytes and other cell types." (PMID 29973666, 2018). "Therefore, TAK-242 does not appear to be an optimal therapy for the treatment of sepsis, whereas its potential efficacy and safety in other diseases linked to excessive TLR4 signaling remain to be investigated." (PMID 30405628, 2018). "Interestingly, it was recently demonstrated that in a model of post-septic mice TLR4 deficiency improves immune paralysis; therefore, modulation of TLR4 activity may be useful in treating sepsis." (PMID 29312312, 2017). "Of note, cell type-specific gene ablation of Toll-like receptor-4 (TLR4) in hepatocytes led to enhanced macrophage phagocytosis, lower bacterial levels, and improved survival in a model of polymicrobial sepsis caused by cecal ligation and puncture without antibiotic therapy." (PMID 28628637, 2017). "The treatment of severe sepsis with TLR4 antagonist may be limited to selected patients." (PMID 29075648, 2017). "Therefore, Mincle could reduce GRK2 expression in sepsis both directly and indirectly by downregulating TLR4 signaling." (PMID 28112221, 2017). "By stimulating leukocytes through pattern-recognition receptors such as TLR4, this model potentially represents microbial inflammation—as might occur in horses with colitis or sepsis—but also inflammatory processes such as laminitis in which damage-associated molecular pathogens are likely involved." (PMID 29034249, 2017). "As will become evident, TLR4 activation may affect both glomerular and tubular processes and experimental data describes a significant improvement in renal function if TLR4 is inhibited in sepsis." (PMID 27602552, 2017). "However, TLR4 is significantly up regulated in the sepsis cohort, compared to healthy controls." (PMID 28628607, 2017). "Although one may deduce from these findings that the putatively hypoactive TLR4 +3725G/G genotype increases susceptibility to infectious diseases, the TLR +3725G/G genotype was associated with a lower risk of developing sepsis in China, suggesting this to be unlikely." (PMID 28484092, 2017). "Thus, inhibition of the TLR4 signaling axis might be a useful method for preventing or reversing LPS-induced muscle wasting in patients with sepsis or metabolic endotoxemia." (PMID 28742154, 2017).